IL1B (interleukin 1 beta)
Diseases named in the same sentence as IL1B in open-access papers (continued):
Sharing a sentence is not in itself a finding about the gene and the disease.
Sepsis (continued). "Through transcriptome analysis of sepsis patients, we identified significant immune suppression in the SP subgroup, as evidenced by the reduced levels of key cytokines such as IL1B and CCL4 in PBMCs." (PMID 39438692, 2024). "Curcumin was found to improve survival and regulate proinflammatory cytokines (TNF-α, IL-6 and IL-1β) and anti-inflammatory cytokines (IL-2 and IL-10) in mice with sepsis/ALI induced by CLP." (PMID 39051370, 2024). "For example, in the context of infectious diseases, anakinra, and canakinumab have been used successfully to inhibit IL-1β and treat conditions such as sepsis and septic shock." (PMID 38251210, 2024). "In the initial stage of sepsis, an intense inflammatory response is ignited, leading to a surge of large amounts of inflammatory factors (e.g., IL-1β, TNF-α), which in turn creates a cytokine storm." (PMID 39720715, 2024). "TNF-α and IL-1β serve as prominent inflammatory mediators initiating the immunopathological features of sepsis-induced shock." (PMID 39200042, 2024). "We believe these two concurrent events led to an enhanced interaction between IFN-γ, TNF-α and monocytes, resulting in an improved phagocytic ability of monocytes during sepsis, and the production of IL-1β." (PMID 38898888, 2024). "Overall, sepsis strongly enhanced the IL-6 (> eightfold), TNFα (> 32-fold) and IL-1β (25-fold) gene expression." (PMID 39497013, 2024). "Reduction in IL-1β in the PF of KO mice compared to WT mice indicates that the NLRP6 inflammasome is activated during sepsis." (PMID 38720893, 2024). "Strikingly, we find that the pairwise effects of tumor necrosis factor plus interleukin (IL)-18, interferon-gamma or IL-1β suffice to mirror the impact of sepsis across tissues." (PMID 38191855, 2024). "Similar to previous studies, our ICU-sepsis group displayed significantly increased interleukin (IL)-18, IL-1β, IL-6, CXCL-8, IL-10 and MCP-1 compared to either or both of the ICU-non-sepsis patient and healthy cohorts." (PMID 38410714, 2024). "Meloxicam-treated sepsis mice in high IL-6 responders had increased liver IL-1β levels compared to Metamizole-treated ones (2.25-fold, adj.P=0.030)." (PMID 39281680, 2024). "The role of mature IL‐1β levels is crucial in this transition from acute to chronic inflammation during sepsis." (PMID 39370294, 2024). "In the early stage of sepsis, monocytes/macrophages are rapidly recruited and release many inflammatory cytokines (e.g. IL-1β, IFN-γ, IL-6, TNF-α, and IL-10); subsequently, chemokines are released and acted on involved organs." (PMID 39320524, 2024). "Other articles showed that the miR-31-5p/GSDMD Axis can regulate pyroptosis and miR-31-5p overexpressing can alleviate the level of TNF‐α, IL‐6 and IL‐1β in sepsis-induced pyroptosis." (PMID 38267979, 2024). "The levels of IL-1β and IL-6 appear to correlate with the severity of sepsis, as they are found at higher levels in deceased patients compared to survivors." (PMID 39063011, 2024). "In the context of sepsis, IL-1β plays a crucial role beyond the initial cytokine response and significantly influences the complex cytokine network." (PMID 39056754, 2024). "IL-1β is one of the major pro-inflammatory cytokines in the course of sepsis/endotoxemia and is produced primarily by monocytes/macrophages." (PMID 38008825, 2024). "While the expression of proinflammatory factors in sepsis (IL-6, IL-1β and TNF-α), which contributed to septic shock, were decreased." (PMID 38166628, 2024). "In sepsis, an increased level of IL-1β can contribute to the development of systemic inflammation and organ dysfunction." (PMID 38251210, 2024). "For instance, IL-1β, produced by activated macrophages and monocytes, mediates sepsis-induced organ dysfunction, such as cardiomyopathy, and inhibition of the NLRP3/IL-1β axis has been shown to be protective in animal models." (PMID 39205680, 2024).
Sepsis (continued). "IL-1b has been shown to be expressed in myocytes in rodent models of sepsis and is considered to be a key mediator of muscle atrophy in this context." (PMID 39012665, 2024). "Namely, it prevents the apoptosis of Purkinje cells by lowering the levels of pro-inflammatory cytokines (IL-6, TNF-α, IL-1β) that are elevated during sepsis and thus prevents sepsis-induced apoptosis in the brain." (PMID 39204155, 2024). "We proved that Fen and Melo significantly alleviated severe inflammation and reduced TNF-α, IL-1β, and IL-6 production in LPS-induced sepsis models, thus warranting further exploration of their role in sepsis clinical treatment." (PMID 39628572, 2024). "TNF-α, IL-1β and IL-6 are pro-inflammatory cytokines that play a central role in the pathogenesis of sepsis." (PMID 39885929, 2024). "The NLRP3 inflammasome, upregulated in sepsis, triggers the release of IL-1β, dependent on cell pH and facilitated by aquaporin-mediated water influx in macrophages." (PMID 39544938, 2024). "IL-1β also disrupts the excitatory-to-inhibitory GABA switch during early CNS development in the context of neonatal sepsis." (PMID 38665289, 2024). "Such preventive effects of α-GalCer pretreatment on sepsis development were attributed to reduced pro-inflammatory cytokine production (i.e., TNFα and IL1β) and immune cell infiltration to the liver." (PMID 39355237, 2024). "Like inflammation due to sterile lung injury and repetitive LPS injections, peripherally induced inflammation in our rat model of sepsis triggered an increase in the concentration of the proinflammatory cytokines IL-1β, IL-6 and IL-17 in the brainstem." (PMID 38331902, 2024). "The pathophysiology of sepsis is characterized by hyperactive and dysregulated endogenous inflammatory mediators, including IL-1β, IL-18, and TNF-α." (PMID 38584827, 2024). "Despite the promising theoretical framework suggesting the potential of targeting IL-1β for sepsis treatment, clinical trials involving anakinra, an IL-1β receptor antagonist, have not demonstrated a significant improvement in patient outcomes." (PMID 39056754, 2024). "This review summarizes recent advances in microglia activation-induced excessive IL-1β release and the molecular signaling pathways involved in IL-1β-induced cognitive dysfunction among sepsis survivors." (PMID 38665289, 2024). "Pharmacological inhibition of NLRP3 not only reduces the expression of IL-1β, but also alleviates cognition impairment after sepsis." (PMID 38665289, 2024). "In acute stage of sepsis, the hyper-activated immune response including the increased IL-6, IL-1β and TNFα, as well as immune cell infiltration are the major causes for the multiple organ damages." (PMID 39726718, 2024). "While the study indicates that PI4P promotes lipid peroxidation in macrophages, leading to IL-1β secretion, the focus of that research was on pyroptosis in bone marrow-derived macrophages within a sepsis model." (PMID 39309491, 2024). "Correspondingly, quercetin significantly reduced serum levels of IL-1β and IL-18 in the mice with acute lethal sepsis." (PMID 39769989, 2024). "In our study, we observed in mice that CLP-induced sepsis resulted in decreased survival, increased release of the pro-inflammatory cytokines IL-1β, IL-18, and TNF-α, and cardiac dysfunction." (PMID 38584827, 2024). "Based on the importance of TNF-α and IL-1β as inflammatory cytokines in sepsis, our laboratory conducted drug screening involving over 2300 compounds to identify those capable of simultaneously inhibiting TNF-α and IL-1β secretion." (PMID 39200042, 2024). "Comparing βMSCs to naive MSCs, the findings showed that systemic administration of IL-1β-pretreated MSCs (βMSCs) improved the symptoms of murine sepsis and increased the survival rate more effectively." (PMID 38756232, 2024).
Sepsis (continued). "IL-1β priming of MSCs significantly enhanced MSC-derived EV protection in CLP models of sepsis by suppressing macrophage activation and promoting M2 polarization, leading to reduced expression of TNF-α, iNOS and increased expression of IL-10 and ARG-1." (PMID 38247814, 2024). "The intensification of P2X7R expression and activation subsequent to sepsis triggers the production of pro-inflammatory cytokines (IL-1β and TNF-α), thereby inducing tissue damage." (PMID 38546748, 2024). "We have shown that sepsis in mice activates the NLRP3 inflammasome, leading to the release of IL-1β, IL-6, and other cytokines and chemokines, causing cardiomyocyte (CM) dysfunction." (PMID 39201339, 2024). "By decorating the corresponding antibodies on the surface of barcodes, the microneedle sensors showed accurate, specific and multiplexed detection of TNF‐α, IL‐1β and IL‐6 in a sepsis mice model." (PMID 38225744, 2024). "IL-1β is not only upregulated early in sepsis but also acts as a key player in triggering the release of other cytokines." (PMID 39056754, 2024). "A significant upregulation of circMAPK1 was observed in patients suffering from sepsis-induced lung injury, along with elevated serum levels of the inflammatory cytokines IL-1β and IL-18." (PMID 39300342, 2024). "Discussion: Therefore, our findings demonstrated that LBT effectively inhibits the production of inflammatory cytokines (IL-6, TNF-α, and IL-1β) and mitigates sepsis induced by LPS through modulating macrophages' ability to generate these cytokines." (PMID 38799158, 2024). "Sepsis can lead to the excessive production of pro-inflammatory cytokines such as interleukin-6 (IL-6), interleukin-1 beta (IL-1β), and tumor necrosis factor-alpha (TNF-α)." (PMID 39273060, 2024). "They assessed the therapeutic effects of IL-1β, a pro-inflammatory cytokine that is abundant in the early stages of sepsis, as a pretreatment for hUC-MSCs in a model of sepsis brought on by cecal ligation and puncture (CLP)." (PMID 38756232, 2024). "Among these pro-inflammatory cytokines, IL-1β is particularly important within the CNS after sepsis." (PMID 38665289, 2024). "This study shows that Salmonella triggers the production of interleukin 1-beta, which induces the host to kill protective members of the microbiota thereby helping Salmonella to colonize the gut, and drives mortality during sepsis." (PMID 38236896, 2024). "This suppression reduces the levels of TNF-α, IL-6, and IL-1β within the body during sepsis, diminishing the inflammatory response and sepsis-induced multiorgan dysfunction." (PMID 39234245, 2024). "TNF-α, IL-1β and IL-6 belong to the most important systemic pro-inflammatory factors undergoing activation at the onset of sepsis." (PMID 39497013, 2024). "This combined treatment brought both IL-1β and TNF-α levels down to near-control values, underlining the synergistic potential of Vit C and CoQ10 in mitigating the inflammatory response in sepsis-induced cardiac injury." (PMID 38326366, 2024). "Sepsis is associated with high levels of inflammatory cytokines such as TNF-α, IL-1β, IL-6, and IL-10." (PMID 39597952, 2024). "Recent studies suggest that the release of interleukin-1β (IL-1β) following activation of microglial cells plays a crucial role in the development of long-lasting neuroinflammation after the initial sepsis episode." (PMID 38665289, 2024). "If stress reactions such as burns and sepsis occur, IL‐1β secretion can be abnormally elevated and positively correlated with the condition, but IL‐1β overexpression can further exacerbate inflammatory reactions and even cause multiorgan failure." (PMID 39692539, 2024). "The effects of TNF plus IL-18, IFN-γ or IL-1β encompassed a high proportion of sepsis biomarker genes, 45.7% (118/258), 43.8% (113/258) or 32.6% (84/258), respectively, compared to the other 12 cytokine pairs tested (8.1% ± 7.3% s.d.)." (PMID 38191855, 2024).
Sepsis (continued). "Overall, CLP sepsis strongly enhanced the IL-6 (> sixfold) (TNFα (> 23-fold), IL-1β (> twofold), IL-1ra (> 22-fold) MCP-1 (> 13-fold) gene expression in the hypothalamus." (PMID 39497013, 2024). "High concentrations of IL-1β were observed in inflammatory conditions such as Cytauxzoon felis infection, mesenteric ischemia, and sepsis in cats instead of obesity." (PMID 39328456, 2024). "It has been observed that excessive IL-1β also suppresses the function and expression of glutamatergic receptors in sepsis models." (PMID 38665289, 2024). "Our data support a model whereby a few elements of cytokine information—TNF plus IL-18, IFN-γ or IL-1β—suffice to explain a large fraction of the molecular and cellular effects of sepsis across tissues." (PMID 38191855, 2024). "In mouse models of sepsis, OI has been shown to prolong survival and decrease IL-1β and TNF release in response to LPS challenge." (PMID 37730914, 2023). "The progression of sepsis is significantly influenced by the involvement of crucial cytokines such as IL-1β, IL-18, IL-6, IL-12, IL-17, and others." (PMID 38035100, 2023). "Considerable researches have proved that PQQ has a positive effect on inflammatory diseases such as obesity, diabetes, and sepsis via the mediation of pro-inflammatory cytokine such as IL-6, IL-1β and TNF-α." (PMID 37935689, 2023). "In the comparison between septic shock and sepsis groups, we found hypomethylation of IL1B (septic shock group 20% hypomethylated compared to sepsis group) and TNFAIP8 (septic shock group 10% hypomethylated compared to sepsis group)." (PMID 38235139, 2023). "Meanwhile, pneumonia-induced sepsis patients exhibited activation of NLRP3 inflammasome and production of the pyroptosis-associated pro-inflammatory cytokines IL-1β and IL-18." (PMID 36923408, 2023). "Broad-spectrum caspase inhibitors Z-VAD-FMK and VX-166 can reduce IL-1β and IL-18 release and show significant therapeutic effects against sepsis in human patients and rodent models." (PMID 36756123, 2023). "In this article, sepsis dramatically increased the levels of the inflammatory cytokines IL-1β, IL-6, and TNF-α, although this rise was reduced following PTP treatment." (PMID 37361224, 2023). "Impressively, A1 expression reduced sepsis‐induced IL‐1β activation in mice exposed to NOMVs despite us failing to observe any depletion of innate immune cells and/or signs of local inflammation." (PMID 37846472, 2023). "We observed a sustained neuroinflammatory process in these surviving animals, and 13 days after sepsis induction, we detected increased IL-1β and TNF-α levels in both structures (hippocampus and cerebral cortex) of septic-surviving WT mice." (PMID 37153798, 2023). "Meanwhile, in sepsis-induced cardiomyopathy, IL-1β contributed to myocardial dysfunction by inducing cardiac atrophy, impairing contraction and relaxation of cardiomyocytes, and boosting inflammatory cytokine expression levels." (PMID 38029224, 2023). "In conclusion, long-lasting neuroinflammation following neonatal sepsis was characterized by sustained IL-1β production within the brain, which subsequently led to necroptosis activation and neurodevelopment deficit." (PMID 37834141, 2023). "The induction of sepsis by CLP or the treatment with morphine significantly increased the level of serum IL1β compared to saline treated rats (P < 0.05)." (PMID 38052832, 2023). "We observed that sepsis increased circulating inflammation markers, such as TNFα and IL-1β, as well as mitochondrial oxidative stress in heart tissue." (PMID 37147703, 2023). "Serum levels of IL-1β and IL-6 also significantly decreased with the use of curcumin in the treatment of sepsis, while IL-10 showed increased plasma levels." (PMID 36756300, 2023). "By producing inflammatory mediators, such as cytokines, chemokines, inducible nitric oxide synthase (iNOS), IL-1β and free radicals such as ROS, microglia disrupt neuronal functions and trigger neuronal damage during sepsis." (PMID 36445634, 2023).
Sepsis (continued). "Recently, it was demonstrated that CD38 deficient mice increased the expression of IL-1β and MCP-1 and aggravated lung injury through TLR4/ERK/NF-κB pathway in sepsis." (PMID 36998049, 2023). "Pro-inflammatory cytokines that are believed to be involved in excessive inflammation in sepsis are TNFα (tumor necrosis factor-alpha), IL-1β (interleukin-1β), IL-12 (interleukin-12), and IL-18 (interleukin-18)." (PMID 37627293, 2023). "Reports from as early as 1993 revealed increased IL-1β abundance in plasma from 10 newborns with clinical sepsis, in addition to increased TNF and IL-6, as compared to 22 healthy controls." (PMID 36769133, 2023). "On the other hand, injection of LPS in mice induces a strong, short-term increase of plasma proinflammatory cytokines (e.g., TNF-α, IL-1β and IL-6), in comparison to the lower and progressive cytokine increase in human sepsis [,48]." (PMID 37456011, 2023). "The magnitude of difference between IL-1β levels observed in COVID-19 (about 1.0 pg./mL see Step 2d) or sepsis (approximately 20 pg./mL) compared to IL-1 amounts capable of causing severe disease in humans appears to span orders of magnitude." (PMID 37928695, 2023). "In this study, we found that PT pretreatment significantly reduced the levels of serum TNF-α, IL-1β, and IL-6 induced by sepsis." (PMID 38152336, 2023). "ROS and RNS regulate innate immunity through direct damage or activation of the transcription factor NF-κB, enhancing the production of TNF-α, IL-1β, IL-6, IL-8, IL-17, and IL-18 to modulate vascular EC dysfunction during sepsis." (PMID 36445634, 2023). "As far as cytokines are concerned, IL-8 promotes NETs release in sepsis as well as in COVID-19, while IL-1β is rather particular for SARS-CoV-2 infection." (PMID 36675530, 2023). "As expected, the levels inflammatory cytokines TNF-α, IL-1β, IL-6 were increased in serum and lung in sepsis mice compared with control group." (PMID 37494665, 2023). "IL-1β derived from activated microglia is the key molecule responsible for the hippocampal synaptic deficits observed in sepsis." (PMID 37891821, 2023). "In neutrophils, GSDMD-NT is transported to azurophilic granules and autophagosomes, releasing IL-1β through autophagy-dependent pathways, which provide the rationale for neutrophil hyperactivation in sepsis." (PMID 38022612, 2023). "During liver failure in an experimental model of sepsis in rats, glucose metabolism is disturbed, transaminase activity increases, and levels of IL-1β, TNF-α, and IL-6 increase." (PMID 38203627, 2023). "First, treatment of rats with morphine or the induction of sepsis by CLP caused hippocampal cellular defects, rises in serum IL-1β, and falls in blood pressure." (PMID 38052832, 2023). "Moraes and others verified microglial and astrocytic activation in the brain of mice 24 h after sepsis induction, attributing the main source of cognitive deficit to IL-1β released from microglia." (PMID 37153798, 2023). "The study found significantly higher levels of pro-inflammatory cytokines (TNFa, IL1B, and IL-6) in the lung tissue of the sepsis and vehicle groups compared to the sham group." (PMID 37675176, 2023). "Previous reports indicated that the LPS-induced release of HMGB1 was associated with sepsis and that HMGB1 is an inflammatory mediator that can increase the levels of TNF-α, IL-6 and IL-1β." (PMID 38026444, 2023). "IL-1β has been found to increase endothelial permeability by inhibiting the transcription of VE-cadherin, suggesting that IL-1β is an important cytokine in the pathogenesis of ARDS induced by sepsis." (PMID 38035100, 2023). "It was reported that IL-1β protects against sepsis by activating the proliferation and differentiation of bone marrow cells into dendritic cells." (PMID 38029224, 2023). "Relative to the sepsis mice, mice treated with sphinganine exhibited strongly enhanced colon length (p < 0.05), as well as markedly diminished D-lactic acid, IL-1β, and IL-6 contents (p < 0.05)." (PMID 37292192, 2023).